LYL1 (LYL1 basic helix-loop-helix family member)
Synonyms: bHLHa18
Tractability: No criterion of Open Targets' tractability assessment is met for any kind of drug.
Gene: Protein-coding gene on chromosome 19 (13,099,033 to 13,103,161, reverse strand). Ensembl gene ENSG00000104903.
Subcellular location: Nucleus
Subcellular location (Human Protein Atlas): Nucleoplasm
Pathways (Reactome):
Signal Transduction: NGF-stimulated transcription
Gene Ontology:
Molecular function: DNA binding; protein binding; DNA-binding transcription factor activity, RNA polymerase II-specific; RNA polymerase II cis-regulatory region sequence-specific DNA binding; protein dimerization activity
Biological process: blood vessel maturation; positive regulation of DNA-templated transcription; regulation of DNA-templated transcription; B cell differentiation; definitive hemopoiesis; regulation of transcription by RNA polymerase II
Cellular component: chromatin; nucleoplasm; nucleus
Genetic constraint (gnomAD): Loss-of-function variants: 4 observed, 7.38 expected, observed/expected ratio (o/e) 0.54, 90% interval 0.27 to 1.24. That is too few expected variants to judge how well the gene tolerates losing a copy. Missense variants: 356 observed, 269.67 expected, observed/expected ratio (o/e) 1.32, 90% interval 1.21 to 1.44. Synonymous variants: 179 observed, 115.99 expected, observed/expected ratio (o/e) 1.54, 90% interval 1.37 to 1.75.
Homologues: Orthologues: chimpanzee LYL1 (99% identical), dog LYL1 (89% identical), pig LYL1 (87% identical), rat Lyl1 (79% identical), guinea pig LYL1 (79% identical), mouse Lyl1 (78% identical), macaque LYL1 (58% identical), tropical clawed frog lyl1 (44% identical). Paralogues in human: TAL1 (36% identical), TAL2 (19% identical), NHLH2 (16% identical), NHLH1 (16% identical).
Diseases named in the same sentence as LYL1 in open-access papers:
LYL1 is named in the same sentence as 38 diseases in open-access papers, as found by Europe PMC text mining. Sharing a sentence is not in itself a finding about the gene and the disease. The quoted sentences say what the papers report.
leukemia (13 papers, 2010 to 2024). A malignant (clonal) hematologic disorder, involving hematopoietic stem cells and characterized by the presence of primitive or atypical myeloid or lymphoid cells in the bone marrow and the blood. "In summary, we provide evidence to support novel, non-leukemia-associated functions of Lyl1 during bacterial infections." (PMID 36119114, 2022). "LYL1 has an important role in hematopoietic stem cell biology and normal hematopoiesis, while its expression has been associated with the development of leukemia." (PMID 25035669, 2014). "Therefore, while TAL1:E protein or LYL1:E protein dimers in T-ALL regulate leukemia-associated genes, expression of TAL1 and LYL1 can also interrupt the function of E protein homodimers." (PMID 35514954, 2022). "Microarray analysis revealed that LMO2 expressing thymocytes have higher Lyl1 expression compared to wild type thymocytes indicating a potential feed-forward mechanism reminiscent of the mechanism seen in TAL1 expressing leukemias." (PMID 35514954, 2022). "Lymphoblastic leukemia 1 (Lyl1) is a well-studied transcription factor known to exhibit oncogenic potential in various forms of leukemia with pivotal roles in hematopoietic stem cell biology." (PMID 36119114, 2022). "In contrast, deletion of Lyl1 significantly increases leukemia latency in LMO2 transgenic mice suggesting that LYL1 supports transformation." (PMID 35514954, 2022). "The basic helix-loop-helix transcription factors Tal1 and Lyl1 play a major role in the regulation of gene expression in the hematopoietic system and are involved in human leukemia." (PMID 24086757, 2013). "Tal2, which belongs to the same family of transcription factors as Tal1 and Lyl1, is also involved in human leukaemia." (PMID 24086757, 2013). "Our findings set a solid foundation for further basic science and clinical explorations aimed at understanding the mechanisms of LYL1 upregulation and their role in leukemia." (PMID 20844761, 2010). "LYL1 codes for a transcriptional factor involved in leukemia progression." (PMID 38328782, 2024). "LYL1 is a transcriptional co-factor with oncogenic activity in leukemia." (PMID 39668349, 2024). "However, LYL1+ and TAL1+ leukemias have unique gene expression profiles and LYL1+ leukemias tend to be related to immature CD4-CD8- T cell progenitors." (PMID 35514954, 2022). "What remains unknown is the nature of these mechanisms and how they contribute to the role of LYL1 in leukemia." (PMID 20844761, 2010). "LYL1 has an important role in hematopoietic stem cell biology, normal hematopoiesis and leukemia." (PMID 20844761, 2010). "For example, LYL1, an oncogene that is aberrantly expressed in diverse subtypes of AML, assembles with MYB in leukemia cells examined in our study, similar to its functional homologue TAL1 in cases of T-ALL." (PMID 33527899, 2021). "It will be important to determine how aberrant co-expression of such oncogenic regulatory complex co-factors is induced in leukemia cells by diverse oncogenes, such as for example by kinase-dependent dysregulation of transcription factor assembly recently described for MEF2C and LYL1." (PMID 33527899, 2021). "In contrast to Sca1‐Lmo2 T‐ALL, Lmo2 was expressed in Sca1‐Lmo2 + nu/nu leukemia and expression array data showed enrichment in human early T‐cell precursor (ETP) ALL genes, in agreement with human ETP ALL cases that commonly showed LMO2/LYL1 deregulation." (PMID 29880602, 2018).
acute lymphoblastic leukemia (7 papers, 2014 to 2025). Leukemia with an acute onset, characterized by the presence of lymphoblasts in the bone marrow and the peripheral blood. "Many researchers have focused on the expression of LYL1 levels in acute lymphoblastic leukemia, while only a few studies on expression of this factor in AML are available." (PMID 25035669, 2014). "Approximately 60% of T-ALL cases also have mutations that augment expression of the transcription factors T acute lymphoblastic leukemia antigen 1 (TAL1), also called Stem Cell Leukemia (SCL), and lymphocytic leukemia antigen 1 (LYL1)." (PMID 35514954, 2022).
T cell acute leukemia (7 papers, 2010 to 2025). "As a member of basic helix-loop-helix transcription factor family, the LYL1 gene is also known to regulate cell proliferation and differentiation, and a form of T-cell acute lymphoblastic leukaemia has been linked to a chromosomal aberration of LYL1." (PMID 29716549, 2018). "Upregulation of LYL1 has been linked to a subtype of T-cell acute lymphoblastic leukemia defined by a stem-like phenotype and an unfavorable prognosis." (PMID 20844761, 2010). "The basic helix-loop-helix proteins TAL1, LYL1 and the LIM-only protein LMO2 were identified from the breakpoints of chromosomal translocations associated with T cell acute leukemia." (PMID 35508511, 2022). "There is evidence in the literature that NF-κB2 is involved in oncogenesis in T-cell ALL as a result of LYL1 translocation." (PMID 25912249, 2016). "The lymphoblastic leukemia-derived sequence 1 (LYL1) gene, which encodes a basic helix-loop helix, was first identified with human T-cell acute leukemia." (PMID 25035669, 2014). "The Lymphoblastic leukemia 1 (LYL1) gene is a proto-oncogenic transcription factor found upregulated in patients with T-cell acute lymphoblastic leukemia (T-cell ALL)." (PMID 20844761, 2010).
acute myeloid leukemia (6 papers, 2014 to 2024). Acute myeloid leukemia (AML) is a group of neoplasms arising from precursor cells committed to the myeloid cell-line differentiation. "In LYL1/LMO2 only few rearrangements were found, underlying the stem cell character of LYL1/LMO2 with similarities to acute myeloid leukemia (AML)." (PMID 38744920, 2024). "LYL1 expression was found in 68.2%, 75%, and 77.8% of cases of acute myeloid leukemia, CML crisis, and MDS, respectively." (PMID 25035669, 2014). "It was shown that LYL1 preferentially co-activates gene expression in acute myeloid leukemia (AML)." (PMID 39668349, 2024).
lymphoma (3 papers, 2012 to 2022). A malignant (clonal) proliferation of B- lymphocytes or T- lymphocytes which involves the lymph nodes, bone marrow and/or extranodal sites. "In addition, we show that T-cell specific activation of MN1 in combination with loss of Pten increases tumour penetrance and stimulates the formation of Lyl1+ murine T-cell lymphoblastic leukemias or lymphomas (T-ALL/T-LBL)." (PMID 31332244, 2019).
osteosarcoma (3 papers, 2018 to 2022). A usually aggressive malignant bone-forming mesenchymal neoplasm, predominantly affecting adolescents and young adults. "Previous studies have shown that LYL1 can play a role in renal clear cell carcinoma and osteosarcoma, and copy number amplification occurs in glioma." (PMID 35958877, 2022). "LYL1 expression also showed differences between osteosarcoma and control samples, and the expression of LYL1 was significantly decreased in osteosarcoma cell lines compared to normal cells." (PMID 35842703, 2022).
stem cell leukemia (3 papers, 2019 to 2022). "Aside from lymphoid lineage-specific roles, recent studies show that Lyl1 modulates the development of primitive macrophage progenitors, and microglia at early embryonic stages and compensates for the loss of stem cell leukemia (SCL) in megakaryopoiesis and platelet function." (PMID 36119114, 2022). "LYL1 is able to maintain primitive erythropoiesis, and it was reported to bind to a subset of stem cell leukemia (SCL) targets according to ChIP-seq analysis in a human erythroleukemia cell line." (PMID 35842703, 2022). "Stem cell leukemia (SCL) is a bHLH transcription factor with high amino acid sequence similarity to Lyl1 and an essential regulator of the hematopoiesis." (PMID 36119114, 2022).
clear cell renal cell carcinoma (2 papers, 2022). "LYL1 was identified to function in clear cell renal cell carcinoma." (PMID 35842703, 2022).
glial tumors (2 papers, 2021 to 2022). "Many of the changes we saw in GS are novel in the setting of glial tumors, including copy number amplification in LYL1 and mutations in PTPN11." (PMID 34162346, 2021).
myelodysplastic syndrome (2 papers, 2014 to 2022). A clonal hematopoietic disorder characterized by dysplasia and ineffective hematopoiesis in one or more of the hematopoietic cell lines. "It has been reported that the expression of LYL1 is higher in AML than in normal bone marrow, and LYL1 was found to be overexpressed in myelodysplastic syndrome compared with normal bone marrow." (PMID 35842703, 2022).
uterine corpus endometrial carcinoma (2 papers, 2018 to 2022). A endometrial carcinoma (disease) that involves the body of uterus. "Somatic amplifications of the LYL1 gene are relatively common occurrences in patients who develop uterine corpus endometrial carcinoma (UCEC) as opposed to other cancers." (PMID 29716549, 2018).
colorectal cancer (1 paper, 2021). A primary or metastatic malignant neoplasm that affects the colon or rectum. "LYL1 gene amplification was associated with the upregulation of cancer-related pathways in uterine corpus endometrial cancer, and RELB gene plays an oncogenic role in colorectal cancer." (PMID 34445498, 2021).
glioblastoma (1 paper, 2022). The most malignant astrocytic tumor (WHO grade IV). "Copy number amplification of LYL1 was reported in gliosarcoma based on a comparison at the molecular level between gliosarcoma patients and glioblastoma patients." (PMID 35842703, 2022).
idiopathic pulmonary arterial hypertension (1 paper, 2020). A sporadic form of pulmonary arterial hypertension (PAH) characterized by elevated pulmonary arterial resistance leading to right heart failure. "Several transcription factors were also found to beupregulated in idiopathic pulmonary arterial hypertension endothelial cellsincluding SOX18, STRA13, LYL1, and ELK, whichhave known roles in regulating endothelial cell phenotype." (PMID 32166015, 2020).
myeloid leukemia (1 paper, 2014). A clonal proliferation of myeloid cells and their precursors in the bone marrow, peripheral blood, and spleen. "We aimed to study the expression percent of oncogene LYL1 in primary and secondary high-risk myeloid leukemia and the impact on prognostic significance in those patients." (PMID 25035669, 2014). "The aim of the present study was to investigate the expression rate of the oncogene LYL1 in primary and high-risk myeloid leukemia and to assess its impact on prognosis." (PMID 25035669, 2014). "However, few studies have looked for the LYL1 expression of leukemic cell lines and clinical cases of myeloid leukemia." (PMID 25035669, 2014).
myeloid malignancies (1 paper, 2024). "In myeloid malignancies, LYL1 has been shown to be associated with a lower remission rate, higher relapse rate, and poor patient survival." (PMID 38328782, 2024).
prostate adenocarcinoma (1 paper, 2024). "Gene correlation study by using datasets of prostate adenocarcinoma (PRAD) from TCGA and of normal prostate samples from GTEx (Genotype-Tissue Expression) from GEPIA for LYL1 and each of the analyzed known AR direct target genes revealed a negative correlation with the LYL1 expression." (PMID 39668349, 2024).
prostate tumors (1 paper, 2024). "In line with this, the expression level of LYL1 was compared between normal tissues, primary and metastatic prostate tumors from a large cohort of PCa samples using RNA-seq data from NIH genomic data common (GDC) data portal." (PMID 39668349, 2024).
T-cell leukemia (1 paper, 2024). A malignant disease of the T-lymphocytes in the bone marrow, thymus, and/or blood. "Therefore, LYL1 is an essential factor for LMO2-driven T-cell leukemia." (PMID 38328782, 2024).
thymoma (1 paper, 2015). A neoplasm arising from the epithelial cells of the thymus.
viral infections (1 paper, 2022). "Instead, differential expression of Lyl1 in whole blood was present in acute systemic viral infections, suggesting a further role for Lyl1 in response to viral pathogens as an early response gene." (PMID 36119114, 2022).
tumor (12 papers, 2012 to 2024). "The correlation analyses indicate that AR signaling in tumor is associated with reduced LYL1 expression in PCa." (PMID 39668349, 2024). "Tumor cells implanted in Lyl1-deficient mice grew faster with increased permeability of tumor vasculature." (PMID 36119114, 2022). "Spearman correlations analysis showed that CRYBB1, CEACAM4, HAMP, and LYL1 were highly positively associated with tumor‐infiltrating lymphocytes in ccRCC." (PMID 34402193, 2021). "In comparison to tumor adjacent tissues, the LYL1 mRNA level is slightly but significantly reduced in PCa tissues indicating a potential tumor suppressive activity of LYL1." (PMID 39668349, 2024). "The data confirm the previous observation exhibiting a slight reduction of LYL1 in primary tumor samples compared to normal tissues and further reduction in metastatic form of PCa." (PMID 39668349, 2024). "For a blood-specific TF, LYL1, we observed that the central coverage at TFBSs was positively correlated with tumor fraction before GC correction (Pearson’s r = 0.41) as expected, but this correlation was much stronger after GC correction (Pearson’s r = 0.63)." (PMID 36463275, 2022). "Tumor microenvironment analysis in TISIDB and GSE73731 confirmed that CRYBB1, CEACAM4, HAMP, and LYL1 were highly related to tumor‐infiltrating lymphocytes." (PMID 34402193, 2021). "Spearman correlations analysis indicated that CRYBB1, CEACAM4, HAMP, and LYL1 were positively related to different kinds of tumor‐infiltrating lymphocytes across many tumor types while RIMBP3C showed consistently statistical insignificance." (PMID 34402193, 2021). "Phenotype association analysis suggested all of hub genes involved in tumor development, and it seems CRYBB1, CEACAM4, and HAMP correlated with ccRCC progression more than another two (RIMBP3C and LYL1)." (PMID 34402193, 2021). "We observed already statistically significant different accessibilities between healthy controls and COAD samples for TFs HNF4A and DLX2 and the other TFs, GRHL2, EVX2, LYL1, and PU.1 showed statistically significant differences at a 1% tumor level." (PMID 31604930, 2019). "For the enhancer in chromosome 19, the target genes are TRMT1, TNPO2, NFIX, DNASE2, PRDX2, NANOS3, and LYL1, which was detected in 22 unique tumor samples." (PMID 29207666, 2017). "The obtained data revealed a reduction of LYL1 in tumor samples and further reduction in metastatic form of cancer suggesting that LYL1 might have tumor suppressive activity in PCa." (PMID 39668349, 2024). "Finally, and given that high MN1 expression is largely restricted to immature human T-ALLs22–26, we also analysed PL and MPL tumours for Lyl1 expression, a well-known marker of murine and human immature T-ALL24,28–31." (PMID 31332244, 2019). "However, and most notably, we observed that MN1 driven Pten null murine T-ALL/T-LBL tumours are characterized by increased levels of Lyl1, a marker of murine and human immature T-ALL24,28–31." (PMID 31332244, 2019). "Next, we compared accessibilities in subsamples with different tumor fractions for TFs selected based on our previous ATAC-seq and nucleosome plasma mapping, i.e., GRHL2, EVX2, DLX2, HNF4A, LYL1, and PU.1." (PMID 31604930, 2019). "Notably, this analysis revealed significantly higher Lyl1 expression levels in MPL tumours as compared to PL counterparts, suggesting that MN1 might, at least in part, be able to drive a more immature oncogenic transcriptional profile during Pten null-driven T-cell transformation." (PMID 31332244, 2019). "The identification of TAL1, LMO2 and LYL1 as new critical regulators of ANG-2 expression definitively establishes the important role of these factors in endothelial cells, and more particularly in tumor angiogenesis and development." (PMID 22792348, 2012).
tumor (continued). "However, multivariate analyses adjusted for tumor histologic type, grade, and stage did not confirm LYL1 gene amplification as an independent prognostic factor for either PFS or OS." (PMID 29716549, 2018).